FGFR3 (fibroblast growth factor receptor 3)
Diseases named in the same sentence as FGFR3 in open-access papers (continued):
Sharing a sentence is not in itself a finding about the gene and the disease.
liver cancer (7 papers, 2019 to 2024). An epithelial or non-epithelial malignant neoplasm that arises from the liver. "According to the analysis, a higher expression of FGFR3 was recorded in the lung, breast, and liver cancers, whereas its expression was significantly decreased in prostate and pancreas cancerous states compared with the respective normal tissues." (PMID 38635549, 2024). "The gene expression analysis revealed over-expression of NTRK1 in liver cancer, whereas, FGFR3 was found over-expressed in lung, breast, and liver cancers compared to their expression in the respective normal tissues." (PMID 38635549, 2024). "In this study, the expression of FGFR3 in ESCC patients was significantly higher than that in tissues adjacent to carcinoma (64.5% (111/172)), which was consistent with FGFR3 expression in gastric and liver cancers in previous studies." (PMID 33381388, 2020). "In addition, we previously found that MPT0E028 and SAHA triggered p-ERK expression with a subsequent increase in the transcription level of fibroblast growth factor receptor 3 in liver cancer cells resistant to sorafenib, an oral multiple kinase inhibitor." (PMID 31142371, 2019).
microcephaly (7 papers, 2018 to 2024). A congenital or acquired developmental disorder in which the circumference of the head is smaller than normal for the person's age and sex. "In another study, zebrafish carrying loss-of-function of Fgfr3 demonstrated craniofacial abnormalities, including microcephaly, Wormian bone formation, and small frontal and parietal bones with delayed osteoblast genesis." (PMID 35118060, 2021). "Silencing of FgfR3 at the neurulation stage results in microcephaly and facial hypoplasia, which is as severe as the effects following Cubn inactivation, whereas inactivation of FgfR1 or FgfR2 does not affect head development." (PMID 37372994, 2023). "Simultaneous inactivation of Cubn and FgfR3 worsens the microcephaly phenotype: the addition of the deficits indicates that Cubn and FgfR3 are partners in Fgf8 signaling at these early stages." (PMID 37372994, 2023). "We confined the region of susceptibility for microcephaly and seizures to a 330 kb sized region that encompassed seven candidate genes (LETM1, FGFR3, WHSC1, NELFA, C4orf48, NAT8LI, and POLN)." (PMID 29721507, 2018). "Furthermore, the Fgfr3 deficient mice have no apparent phenotype in craniofacial skeleton 12,13, while CATSHL syndrome patients exhibit craniofacial skeleton phenotypes such as microcephaly, high palate and wormian bones 1-3." (PMID 32641982, 2020).
oral cancer (7 papers, 2014 to 2025). "FGFR3 mutation is also correlated with poor prognosis in oral cancer." (PMID 33143664, 2020). "As described by Shigeishi (2023), in HPV-positive oral cancers, mutations in the PIK3CA gene are frequently observed, while there are somatic mutations in ZNF750, FGFR3, DDX3X, CASZ1, PTEN, and CYLD, differentiating them from HPV-negative oral cancers." (PMID 40284955, 2025). "In oral cancer, the increase of miR-100 inhibited FGFBP1 and FGFR3, which over-expressed in radio-resistant cells, indirectly corroborate our hypothesis." (PMID 35477450, 2022).
osteochondrodysplasia (7 papers, 2014 to 2026). A term referring to disorders characterized by abnormalities in the development of bones and cartilage. "One of the early reports described a mutation in codon 650 of FGFR3 in a patient with mild form of osteochondrodysplasia and AN (p.K650Q)." (PMID 25505998, 2014). "Taken as a whole, our findings show that FGFR3 is a critical orchestrator of bone repair and provide a rationale for the development of potential treatments for patients with FGFR3-osteochondrodysplasia." (PMID 39837840, 2025). "Together, these data provide rationale for the clinical study of TYRA-300 in children with ACH, HCH, and potentially other FGFR3-related osteochondrodysplasias." (PMID 40178985, 2025). "Among the FGFR3-related osteochondrodysplasias, research programs have been developed using Fgfr3 gene–targeted mouse models to provide mechanistic insights into ACH, with opportunities for therapy." (PMID 37345656, 2023). "Interestingly, FGFR3 antagonists were able to restore the defective mandibular bone repair indicating a potential treatment option for patients with FGFR3-osteochondrodysplasia." (PMID 41535622, 2026). "Additionally, rare protein-damaging missense variation in FGFR3 was the top predictor of osteochondrodysplasia (OR: 61.51, 7.13−12) from analyses in the UK Biobank reported in the AstraZeneca PheWAS Portal." (PMID 38684708, 2024).
Upper tract urothelial carcinoma (7 papers, 2019 to 2024). "Two studies reported on western cohorts downloaded from cancer genome databases, however, revealed a significantly higher mutated frequency of FGFR3 in upper tract urothelial carcinoma (UTUC) compared to UC patients." (PMID 37387501, 2023). "Upper tract urothelial carcinomas, representing less than 10% of urothelial cancers, harbor FGFR3 mutations in up to 60% of high-grade cases." (PMID 37377403, 2023). "Alterations in FGFR3 are found in around 15% of urothelial carcinomas, with a higher frequency in upper-tract urothelial carcinoma (UTUC) and luminal papillary tumors." (PMID 39272913, 2024). "However, up to 20% of advanced urothelial carcinoma and 37% of upper tract urothelial carcinoma (UTUC) demonstrate FGFR3 alterations." (PMID 36358849, 2022).
deafness (6 papers, 2009 to 2025). An inherited or acquired condition characterized by the complete loss of the ability to hear from one or both ears. "As mentioned in the introduction, both gain and loss of function mutations in Fgfr3 lead to deafness and prolonged Fgf-signaling delays PC development." (PMID 23394545, 2013). "In Fgfr3 knockout mice the inner ear defects include failure of pillar cell differentiation and tunnel of Corti formation that result in profound deafness." (PMID 32641982, 2020). "During inner ear development, many genes causing IEM and deafness have been identified, including SLC26A4, EYA1, FGFR3, and TCOF1." (PMID 21961810, 2011). "Fgfr3 knockout mice show skeletal overgrowth and deafness owing to inner ear defects, indicating the role of Fgfr3 in skeletal growth and hearing." (PMID 19192266, 2009). "Consistent with our previous results, low doses of DEX had no rescue effect on deafness in Fgfr3‐CreER; Gjb2loxp/loxp mice." (PMID 39739601, 2025).
neuroblastoma (6 papers, 2013 to 2025). Neuroblastoma (NB) is the most common solid, extracranial childhood tumor. "In pediatric sarcoma databases, the rates of alterations of the FGFR1, FGFR2, FGFR3, and FGFR4 genes were 1.3%, 0.2%, 0.2%, and 2.4%, respectively, while in neuroblastoma tumor samples, the rates of alterations were 0.2% for each." (PMID 40510032, 2025). "It has been reported that HC/A can bind to and activate fibroblast growth factor receptor 3 (FGFR3), which is a tyrosine kinase receptor, in neuroblastoma cells." (PMID 33967844, 2021).
neuropathy (6 papers, 2020 to 2026). A disorder affecting the nervous system that manifests with pain, tingling, numbness, and/or muscle weakness. "Together this work suggests that beyond their role as biomarkers, FGFR3-AbS are pathogenic in small fiber neuropathy by acting directly on DRG neurons." (PMID 41700748, 2026). "Recent studies, which have expanded their inclusion criteria, shed light onto the highly variable clinical manifestation and pattern of neuropathy that is associated with FGFR3 antibodies." (PMID 33588772, 2021). "Though anti-FGFR3 antibodies were originally associated with purely sensory-predominant neuropathies or neuronopathies, recent studies suggest that the associated neuropathy and clinical manifestation can be rather diverse and imprecise." (PMID 33588772, 2021). "Despite its initial association with sensory neuropathies, anti-fibroblast growth factor receptor 3 (FGFR3) antibodies have been since reported with a broad range of neuropathies and clinical features." (PMID 33588772, 2021). "Past studies on FGFR3-related neuropathy suggested an association between sensory neuropathy and FGFR3 antibodies, though a causal relationship is unknown." (PMID 33588772, 2021). "The broad spectrum of clinical features and EMG/NCS results that are seen across multiple studies, including the current study, suggest that neuropathies associated with FGFR3 antibodies have the potential to involve small and large fibers, sensory and motor fibers, and the trigeminal nerve." (PMID 33588772, 2021). "Previous reports also suggest that neuropathy associated with FGFR3 antibodies may be the result of damage to the axons, myelin, or both." (PMID 33588772, 2021). "Among FGFR3 Abs-positive neuropathy patients for example, we recently found five different epitopes on the FGFR3 protein." (PMID 36341350, 2022). "At this time, the significance of anti-FGFR3 antibody in patients with polyneuropathy is unclear, and more studies are needed to understand their role in the pathogenesis of neuropathy." (PMID 33588772, 2021). "Neuropathy related to FGFR3 antibodies can potentially involve small and large fibers, sensory and motor fibers, and even the trigeminal nerve, which contributes to a highly variable clinical presentation." (PMID 33588772, 2021). "Among the 14 patients with positive FGFR3 antibodies and neuropathy included in this study, 100% of patients presented with painful paresthesia and 42.9% showed gait instability." (PMID 33588772, 2021). "Our findings observed that patients with anti-FGFR3 antibody-related polyneuropathy may present with highly variable clinical features, and our paper adds to the literature on this growing subtype of neuropathy." (PMID 33588772, 2021). "Still, the exact role of FGFR3 antibodies in peripheral system diseases such as neuropathies remains unclear." (PMID 33588772, 2021). "The neuropathy associated with FGFR3 antibodies does not seem to be limited to sensory neurons, as motor nerve fiber involvement seems to be common." (PMID 33588772, 2021). "Further, anti-FGFR3 are not exclusive for sensory neuropathies, but can also occur in other neuropathies, questioning the specificity of the test." (PMID 41142778, 2025). "For this reason, we attributed the neuropathy in these three patients to FGFR3 antibodies, rather than their autoimmune conditions." (PMID 33588772, 2021). "We would also like to note that there were four patients in our cohort who were positive for FGFR3 antibody but were subsequently determined to have neuropathy that was not related to the antibody." (PMID 33588772, 2021). "Beyond FGFR3 inhibitors as biomarker-informed therapies, and in the absence of other molecularly informed decisions, the subsequent-line setting will likely utilize chemotherapy in patients who remain fit and without significant neuropathy from EVP." (PMID 38540132, 2024).
neuropathy (continued). "Autoantibodies against fibroblast growth factor receptor 3 define a subset of patients with consistent reports of neuropathic pain harboring a distinct clinical phenotype characterized by small-fiber and non-length-dependent neuropathy, suggesting dorsal root ganglia (DRG) dysfunction." (PMID 41700748, 2026).
Obesity (6 papers, 2018 to 2023). Accumulation of substantial excess body fat. "In this context, understanding whether and how obesity and metabolic complications are also consequences of the FGFR3 mutation is an important question to solve before proposing a treatment." (PMID 29652901, 2018). "However, today, there is an increasing number of evidence suggesting that the early onset and development of this central and atypical obesity may originate in the FGFR3 mutation itself." (PMID 31727132, 2019). "This is in line with previous studies where it was demonstrated that hepatic levels for β-Klotho, FGFR1 and FGFR3 transcripts were significantly increased in patients with obesity." (PMID 33670024, 2021). "Our data are in accordance with them but also establish that the development of a nonconforming obesity is preferentially abdominal and appears to be triggered by the FGFR3 mutation." (PMID 29652901, 2018). "To address the role of the FGF6/9-FGFR3 pathway in human thermogenic function and obesity, we measured the expression of FGF6, FGF9, and FGFR3 in human adipose tissue biopsies." (PMID 32184391, 2020). "Altered DNA methylation in promoters of transcription factor genes (PPARA, KLF15, NR3C1, RORA and ATF4) known to regulate FGF21 expression and its binding receptors and co-factors (FGFR1, FGFR3 and FGFRL1 and KLB) has been revealed in relation to the elevated levels of circulating FGF21 in obesity." (PMID 33670024, 2021). "There is little evidence available so far regarding the FGFR3 gene, therefore, recommendations for these patients should be general, since there is no optimal diet for the prevention or treatment of obesity." (PMID 31727132, 2019).
scoliosis (6 papers, 2015 to 2025). A congenital or acquired spinal deformity characterized by lateral curvature of the spine. "The patient exhibited features such as scoliosis and a trident configuration of the hands all of which can be explained by a mutations in FGFR3 at c.1138 G > A(p.Gly380Arg)." (PMID 27370225, 2016). "FGFR3−/− mice have been characterized with osteopenia, which has been established as a risk factor for curve progression in patients with scoliosis." (PMID 25852647, 2015). "Disruptions in the activities of Sox9+, Fgfr3+, or Dlx5+ progenitors at E10.5 may underlie osteogenic conditions such as scoliosis or long-bone deformities." (PMID 40581360, 2025). "Phenotypes that include scoliosis are also seen in humans and mice with mutations in genes encoding proteins involved in the downstream signaling pathways of cell surface receptors like FGFR3." (PMID 25852647, 2015). "In the current study, PTHrP-1-34 treatment resulted in blunting of the coronal plane scoliosis in FGFR3−/− mice as evidenced by a reduction in the discrepancy between concave and convex lengths of the apical vertebra." (PMID 25852647, 2015). "Development of scoliosis, measured by Cobb angle, in growing FGFR3−/− mice." (PMID 25852647, 2015). "Suffice to say the precise mechanism by which the positive influence of PTHrP-1-34 in correcting progressive scoliosis in growing FGFR3−/− mice awaits additional immunochemical analyses in vivo and detailed analysis of intact spines subjected to controlled loading ex vivo." (PMID 25852647, 2015). "Kyphosis and scoliosis are common with ACH and are also observed in the Fgfr3Y367C/+ mouse model, and Fgfr3 is expressed in the intervertebral discs of Fgfr3Y367C/+ mice." (PMID 40178985, 2025). "Measurement of the Cobb angle on serial antero–posterior radiographs of the spines of growing mice revealed 62 of 63 FGFR3−/− mice and no FGFR3+/+ mice met the criteria for scoliosis at the time of euthanasia between 4 and 6 months of age." (PMID 25852647, 2015). "Continuous release of PTHrP-1-34 from pellets implanted adjacent to the thoracic spine at 1 month of age inhibited progression of scoliosis but did not alter the development of kyphosis in FGFR3−/− mice." (PMID 25852647, 2015).
Ta (6 papers, 2012 to 2026). "In Ta tumors, the most frequent gene variants were FGFR3 (48%) and PIK3CA (26%), and the most common amplifications were AKT1 (24%), FGFR3 (13%), MYCN (11%), and CCND1 (11%)." (PMID 39410541, 2024). "Our analysis identified two subgroups in Ta tumors: one with FGFR3 alterations linked to LG tumors and favorable outcomes, and another with alterations in ERBB2, PIK3CA, and ERBB3 mutations, and FGFR1, CCND1, and MYC amplifications, associated mostly with HG tumors and poorer prognosis." (PMID 39410541, 2024). "In addition, low miR-7 expression in Ta tumor has been shown to be in line with the frequent activation of FGFR3 signaling, and miR-7 is an important member of the miRNA signature for FGFR3 mutated cases in BC." (PMID 28388561, 2017). "Non-invasive Ta papillary tumors commonly have activating mutations in FGFR3 (as seen here), or mutation in one of the RAS genes (mutually exclusive with FGFR3 mutation), and loss of one chromosome 9." (PMID 23593348, 2013). "Interestingly, these two pathways are also activated by Fibroblast Growth Factor Receptor 3 (FGFR3) that is commonly mutated and constitutively activated in Ta tumors." (PMID 28882129, 2017).
thyroid cancer (6 papers, 2009 to 2024). "However, TERTp mutation may be a second genetic event following oncogenic activation, such as IDH mutation in diffuse gliomas, BRAF V600E mutation in thyroid cancer, and FGFR3 mutation in urothelial carcinoma." (PMID 37185778, 2023). "FGFR1 and FGFR3 are expressed in well-differentiated thyroid cancers, and ATC cells overexpress FGFR4." (PMID 25295214, 2014). "Similarly, the enrichment of FGFR3 mutations in salivary gland tumors and ERBB4 mutations in thyroid cancers among Asian patients suggests that clinical investigations targeting these alterations need to target demographically diverse patient communities." (PMID 38297963, 2024).
epilepsy (5 papers, 2020 to 2025). A brain disorder characterized by episodes of abnormally increased neuronal discharge resulting in transient episodes of sensory or motor neurological dysfunction, or psychic dysfunction. "FGFR3 fusion was identified in diffuse lower-grade gliomas that have characteristics of long-term epilepsy-associated neuroepithelial tumors (LEAT)." (PMID 41007824, 2025). "This discovery was followed by the identification of FGFR3 mutation in keratinocytic epidermal nevus syndrome in a female with epilepsy since infancy." (PMID 34208656, 2021). "Previous studies have demonstrated that skeletal dysplasia patients with Asn540Lys mutation in the FGFR3 gene have been documented to accompany with medial temporal lobe dysgenesis and epilepsy." (PMID 32830860, 2020). "Other potentially relevant genes displaying the same expression trend were the heparan sulfate proteoglycan GPC2 (a marker of immature neurons), the helix–loop–helix transcription factor ID4 (a marker of postmitotic neurons), and the signaling molecule FGFR3 that has been implicated in epilepsy." (PMID 31820119, 2020). "Interestingly, both FGFR3 and STAT3 have been associated with epilepsy." (PMID 33002329, 2020).
LADD syndrome (5 papers, 2008 to 2024). A multiple congenital anomaly syndrome characterized by hypoplasia, aplasia or atresia of the lacrimal system; anomalies of the ears and hearing loss; hypoplasias, apalsias or atresias of the salivary glands; dental anomalies and digital malformations. "Sequence alterations in the intracellular tyrosine-kinase domains of FGFR2 and FGFR3 were described to be involved in LADD syndrome, and aberrations of the FGF10 gene were found to be associated with both the ALSG and the LADD syndrome." (PMID 19102732, 2008). "LADD syndrome is an autosomal dominant disorder caused due to mutations in one of at least three genes, the fibroblast growth factor receptor 2 (FGFR2), fibroblast growth factor receptor 3 (FGFR3), and fibroblast growth factor 10 (FGF10)." (PMID 27803819, 2016).
lymphoma (5 papers, 2014 to 2023). A malignant (clonal) proliferation of B- lymphocytes or T- lymphocytes which involves the lymph nodes, bone marrow and/or extranodal sites. "A previous study showed that the FGFR3 fusion protein (TEL-FGFR3) induced T-lymphoma and subsequently progressed to AML." (PMID 33584313, 2020). "However, ricolinostat did not cause downregulation of cyclin D1 in lymphoma cell lines, and it remains to be determined whether ricolinostat or other HDAC6 selective inhibitors being developed are effective at downregulating MYC and FGFR3 or other FGFRs." (PMID 29423038, 2018).